PLEKHB1 (pleckstrin homology domain containing B1)
Synonyms: PHRET1; KPL1; PHR1
Tractability: No criterion of Open Targets' tractability assessment is met for any kind of drug.
Gene: Protein-coding gene on chromosome 11 (73,646,178 to 73,662,819, forward strand). Ensembl gene ENSG00000021300.
Subcellular location: Membrane; Cytoplasm
Gene Ontology:
Molecular function: protein binding
Biological process: phototransduction; regulation of cell differentiation
Cellular component: membrane; cytoplasm
Genetic constraint (gnomAD): Loss-of-function variants: 29 observed, 34.39 expected, observed/expected ratio (o/e) 0.84, 90% interval 0.63 to 1.15. The upper end of that interval is the gene's LOEUF score, 1.15, which puts it in group 5 of 6, group 1 being the genes least tolerant of losing a copy. Missense variants: 330 observed, 340.81 expected, observed/expected ratio (o/e) 0.97, 90% interval 0.88 to 1.06. Synonymous variants: 138 observed, 137.23 expected, observed/expected ratio (o/e) 1.01, 90% interval 0.88 to 1.16.
Homologues: Orthologues: chimpanzee PLEKHB1 (99% identical), macaque PLEKHB1 (98% identical), pig PLEKHB1 (95% identical), dog PLEKHB1 (94% identical), guinea pig PLEKHB1 (94% identical), rabbit PLEKHB1 (93% identical), rat Plekhb1 (93% identical), mouse Plekhb1 (74% identical), tropical clawed frog PLEKHB1 (43% identical), zebrafish plekhb1 (35% identical). Paralogues in human: PLEKHB2 (38% identical).
Diseases named in the same sentence as PLEKHB1 in open-access papers:
PLEKHB1 is named in the same sentence as 10 diseases in open-access papers, as found by Europe PMC text mining. Sharing a sentence is not in itself a finding about the gene and the disease. The quoted sentences say what the papers report.
amyotrophic lateral sclerosis (2 papers, 2019 to 2020). Amyotrophic lateral sclerosis (ALS) is a neurodegenerative disease characterized by progressive muscular paralysis reflecting degeneration of motor neurons in the primary motor cortex, corticospinal tracts, brainstem and spinal cord. "Interestingly, mutations in PLEKHB1 have been reported to cause amyotrophic lateral sclerosis, characterized by problems with muscle control and movement (omim.org/entry/105400)." (PMID 31254144, 2019).
osteoporosis (2 papers, 2016 to 2020). A condition of reduced bone mass, with decreased cortical thickness and a decrease in the number and size of the trabeculae of cancellous bone (but normal chemical composition), resulting in increased fracture incidence. "SNPs in associated regions on chromosomes 7 and 11 are proximal to genes PLEKHB1 (chr11), FAM3C (chr7), and WNT16 (chr7), and the latter has been associated with bone mineral density, osteoporosis, and fracture risk." (PMID 27325353, 2016). "Herein, we first found the significant expression of PLEKHA2, PLEKHB1, PNPLA7, SCD, MGST3 and TSNAX in osteoporosis of postmenopausal women, which may be valuable in understanding the pathology mechanism of the disease." (PMID 32496000, 2020).
fibrodysplasia ossificans progressiva (1 paper, 2016). Fibrodysplasia ossificans progressiva (FOP) is a severely disabling heritable disorder of connective tissue characterized by congenital malformations of the great toes and progressive heterotopic ossification that forms qualitatively normal bone in characteristic extraskeletal sites. "PLEKHB1 protein interacts with ACVR1, which is involved in fibrodysplasia ossificans progressiva (FOP), a rare congenital disorder that causes bone formation in muscles, tendons, ligaments, and connective tissues." (PMID 27325353, 2016).
lung carcinoma (1 paper, 2024). "Moreover, five of the remaining genes showed significant results in at least one of the lung cancer types, including LRRC27 and PLEKHB1 in LUAD and ARNTL2, FOSL1, and PTBP3 in LUSC." (PMID 39410631, 2024).
PLEKHB1 also shares sentences with these, for which no sentence is quoted: cancer (2 papers); infection (2); amyloid (1); CNS tumors (1); posttraumatic stress disorder (1); viral infections (1).